TFE3 (transcription factor binding to IGHM enhancer 3)
Diseases named in the same sentence as TFE3 in open-access papers (continued):
Sharing a sentence is not in itself a finding about the gene and the disease.
tumor (continued). "Furthermore, it was found that the expression of TFE3 protein in the RCC correlates with the tumor progression and poor prognosis irrespective of the presence of TFE3 translocation." (PMID 36276115, 2022). "(Immunohistochemical stains showed that the tumor cells were positive for desmin and TFE3, while negative for pancytokeratin, CAM5.2, EMA, chromogranin, synaptophysin, NSE, CD45, SMA, HHF35, myogenin, CD117, DOG1, MUC4, S100, SOX10, HMB45, Melan-A, CD31, ERG, TLE1, STAT6, and Cathepsin-K)." (PMID 35001360, 2022). "Interestingly, we found that upregulated TFE3 was only observed at the protein level and not at the mRNA level in tRCC tumor tissues." (PMID 36470859, 2022). "Additionally, the longest diameter of single tumor size was much larger in TFE3-positive EHEs (8.24 ± 3.14 cm) compared with TFE3-negative EHEs (3.44 ± 0.80 cm, P = 0.0550)." (PMID 26840265, 2016). "In addition to this, it has also been found that TFEB-amplified RCC exhibits a higher tumor aggressiveness than TFEB-rearranged tumors, and the 5-year survival rate for TFEB-amplified RCC is only 48%, while TFEB-translocated RCC progresses more slowly than TFE3-rearranged RCC." (PMID 37367052, 2023). "Immunohistochemical analysis using the recommended minimum antibody panel (CAIX, TFE3, PAX8, HMB-45 and Melan-A, Cathepsin K, AMACR, CK-7, EMA) could be advised routinely for every case of RCC, regardless of the patient′s age and the microscopic features of the tumor." (PMID 35886994, 2022). "Importantly, TFE3 but not TFEB is essential for the survival of tumour cells." (PMID 33145941, 2020). "Tumor cells were negative for CD34, TFE3, STAT6, ALK1, PAX8, AE1/3, and other epithelial, neural, and myogenic markers." (PMID 40948436, 2026). "We crossed TFE3‐RCC mouse models with Hif1α and/or Hif2α knockout mice and found that Hif1α, rather than Hif2α, is essential for tumor development in vivo." (PMID 39807625, 2025). "Immunohistochemical analysis showed that the tumor cells were positive for PAX8, CA-9, CD10, and CK7, but negative for CD117 and TFE3." (PMID 41426332, 2025). "Although TFEB was not detectable in SPN (data not shown), TFE3 and MITF were both highly expressed in SPN compared to other tissue types, including tumor and benign tissues (cohorts 1/2)." (PMID 41310888, 2025). "The tumor cells were immunoreactive for pan-keratin (AE1/AE3) and PAX8, but no reactivity with KRT7, CA9 and TFE3." (PMID 37415400, 2024). "Tumor cells were positive for TFE3 on IHC and while the fluorescence in situ hybridization (FISH) breakapart assay was negative for the TFE3 translocation, morphologic and IHC profiles were consistent with a MiT family translocation RCC." (PMID 39156348, 2024). "All tumour cells were negative for vimentin, CA9, CD10, P504s, CK20, TFE3, TFEB, HMB45, ALK and FOXI1." (PMID 36816543, 2023). "Upon immunohistochemistry (IHC), the tumor cells were positive for HMB45 and TFE3, focally positive for MelanA, while negative for muscle marker." (PMID 36647157, 2023). "Due to the rarity of TFE3-rearranged RCC and the fact that it has not been previously considered as a specific tumor subtype, there are no treatment recommendations for it to date." (PMID 37367052, 2023). "We conclude that, in the absence of FLCN, TFE3 is constitutively active in renal epithelial cells, confirming TFE3 as a bona fide target of the FLCN tumor suppressor." (PMID 33459596, 2021). "By immunohistochemistry, the tumor was positive for CD31, CD34, ERG, and TFE-3 and negative for PCK, CK8/18, EMA, CK19, Glypican3, hepatocytes, and arginase." (PMID 33121478, 2020). "TFE3 expression was increased in high-grade HNSCC and large tumor size, but the difference was not statistically significant." (PMID 26872381, 2016). "The tumor cells did not stain positive for WT1, cytokeratin (CK) 34β12, transcription factor E3 (TFE3), and CD10." (PMID 25081056, 2014).
tumor (continued). "The tumor cells were negative for the BCL3 gene rearrangement, indicating that the BCL3 gene is not the novel gene fusion partner of TFE3 in the case herein presented." (PMID 19450277, 2009). "Additionally, in this case, the tumor cells showed Ki67<5%, and did not express CD117, TFE3, HMB45, or SDHB, while expressing FH and INI1(SMARCB1)." (PMID 41306531, 2025). "Moreover, by immunohistochemistry (IHC), the tumor showed diffuse reactivity for vascular markers, including ERG, CD31, CD34, and D2-40, as well as for TFE3, while being negative for MUC4, CAMTA1, smooth-muscle actin, desmin, S100 and keratins." (PMID 40879254, 2025). "The tumor cells were positive for PAX8, weakly and focally positive for CK20, CKAE1/AE3, CD10, and AMACR, and negative for CK7, CD117, MelanA, HMB45, TFE3, Actin, and ALK." (PMID 38892169, 2024). "In this report, nearly all tumor cells were positive for GATA-3, KRT7, EMA, E-Cadherin, Ksp-Cadherin, 34βE12, and AMACR in varying intensities, focally positive for CD10 and Vimentin, while negative for CD117, TFE3, RCC, and CAIX." (PMID 37143937, 2023). "Few features shared by these tumours and ESC RCC are the polygonal cells with abundant vacuolated cytoplasm and positivity for Melan A. However, the macrocystic areas, lack of papillary pattern, CK20 positivity and negative TFE3 favours ESC RCC." (PMID 34514562, 2022). "Molecular testing performed and interpreted at University of Nebraska, Omaha NE reported the tumor as negative for fusion of the EWSR1 (22q12) and ATF1 (12q13) loci, negative for rearrangement of the TFE3 (Xp11) locus, and negative for fusion of the EWSR1 (22q12) and CREB1 (2q33.3) loci." (PMID 30314519, 2018). "By defining a TFE3-driven epigenomic signature in tRCC cell lines and detecting it in patient plasma using ChIP-seq, we distinguished tRCC from clear-cell RCC (AUC = 0.86) and samples of individuals without evidence of cancer (AUC = 0.92) at low tumor fractions (<1%)." (PMID 41623182, 2026). "All the five tumours in this study had a typical immunophenotype characterized by diffuse positivity for CK7 and negativity for CD117, and were also positive for PAX-8, E-cadherin, FH and SDHB, but negative for vimentin, CD10, P504s, CA9, CK20, TFE3, TFEB, HMB45, and ALK." (PMID 36816543, 2023).
cancer (97 papers, 2010 to 2026). A tumor composed of atypical neoplastic, often pleomorphic cells that invade other tissues. "Both of these genes encode components of the SWI/SNF chromatin remodeling complexes, which are implicated in various cancers, suggesting their potential importance in TFE3-RCC as well." (PMID 39727945, 2024). "Cell viability data and death marker protein expression show that the loss of ATF4, TFE3, or the combination of the two can significantly abrogate DT-061 effects on cancer cell death." (PMID 39349971, 2024). "On the contrary, inhibiting TFEB and TFE3 activity has demonstrated beneficial effects by reducing cancer cell viability and increasing their susceptibility to anticancer therapies." (PMID 38522425, 2024). "The expression and activity of TFE3 are upregulated in many types of human cancers and are associated with the enhanced proliferation and motility of cancer cells." (PMID 37528481, 2023). "Lysosomal-associated transcriptional activity of TFEB and TFE3 is aberrantly activated in some cancers through constitutive nuclear localization, which overrides the brake imposed by nutrient availability on lysosomal functions." (PMID 32686708, 2020). "The expression of the TFEB and TFE3 and their activity are elevated in multiple types of human cancers and associated with enhanced proliferation and motility of these cancer cells." (PMID 33145941, 2020). "The levels of TFEB and TFE3 are elevated in multiple types of human cancers and have been linked with both occurrence and poor prognosis." (PMID 33145941, 2020). "Translocations of TFE3 gene can lead to a significant increase in its protein levels, and thus is associated with a certain type of cancer." (PMID 31043173, 2019). "TFE3 positivity in RCC was significantly associated with shorter cancer specific survival (P < 0.001)." (PMID 24455396, 2013). "In cancers driven by TFEB/TFE3/MITF, expression of genes encoding endolysosomal cation channels, TRPML1, TRPML2 and TPC2, is elevated, and either the knockdown or pharmacological inhibition of these channels attenuates the growth and invasiveness of the tumors." (PMID 35406743, 2022). "Recent studies have linked the accumulation of ROS to TFE3 activation in cancer prognosis." (PMID 34660181, 2021). "TFE3, a transcription factor related to mitochondrial function and cancers, may play a central role in UC-associated carcinogenesis." (PMID 33987007, 2021). "Overall, TFE3, as a transcription factor, plays a crucial role in regulating cellular growth, differentiation, and metabolism, and its aberrant expression may be closely associated with the onset and progression of various cancers." (PMID 39440241, 2024). "Unveiling of these pathogenic mechanisms of TFE3 fusions may benefit the development of new cancer." (PMID 30849994, 2019). "TFE3 was shown to be a powerful regulator controlling the expression of autophagy flux-related genes in a variety of cancers." (PMID 41450945, 2025). "Cancer Cell Line Encyclopedia (CCLE) data indicate that MiaPaCa-2 cells express approximately 50-fold more TFE3 mRNA than TFEB mRNA." (PMID 39869680, 2025). "The results uncover a hierarchical cascade whereby microenvironmental stresses, including glucose limitation, lead MITF, TFEB, and TFE3 to drive distinct biologically important transcription programs that underpin phenotypic transitions in cancer." (PMID 41275493, 2025). "Compared with ordinary papillary renal carcinoma patients, cancer‐specific survival (CSS) for TFE3‐rearranged RCC is significantly poorer." (PMID 38477529, 2024). "We demonstrate that VCP is a likely obligate co-factor of ASPSCR1::TFE3, one of the only such fusion oncoprotein co-factors identified in cancer biology." (PMID 38326311, 2024). "Our research reveals an intrinsic mechanistic vulnerability within cancer cells in the PP2A/TFE3 pathway." (PMID 39349971, 2024).
cancer (continued). "Many prerequisites for gene fusion are established after the breaking of double-stranded DNA; therefore, studies have focused on factors related to the breaking of the Xp11.2 tRCC TFE3 gene to find breakthroughs at the gene level for treating this carcinoma." (PMID 38988705, 2024). "In the early stages of Xp11 tRCC, autophagy activated by TFE3 first suppresses and subsequently promotes the metabolism of cancer cells." (PMID 36906611, 2023). "In the late stage of Xp11tRCC, autophagy activated by TFE3 plays a major role in promoting cancer cell metabolism." (PMID 36906611, 2023). "Given that KEAP1 and NRF2 are frequently mutated in cancer, it will be interesting to explore the involvement of TFEB/TFE3 in NRF2-driven cancers." (PMID 37216554, 2023). "The most studied functions of TFE3 include lysosomal biogenesis promotion, involvement in cancer progression, and autophagy induction." (PMID 36906611, 2023). "The deletion of the TFE3 Rag-binding domain, which is the binding site of TFE3 and active RagGTPases, prevents the phosphorylation of TFE3 by mTORC1 to produce 14-3-3 binding sites and remains in the cytoplasm in carcinoma cells." (PMID 36906611, 2023). "Either the overexpression and/or constitutive nuclear localization of TFEB and TFE3 promote the growth of various types of cancer." (PMID 35406743, 2022). "Transcription factor E3 (TFE3) has been identified as a powerful regulator that controls the autophagic flux-related genes expression in various cancers." (PMID 35462576, 2022). "TFE3, a transcription factor related to mitochondrial function and cancer, seem to play a central role in this process." (PMID 33987007, 2021). "All these results highlight an important role of mTORC1/TFEB/TFE3 feedback loop in cancer biology and encourage to better-characterize how mTORC1-FLCN/FNIP-AMPK interplay to regulate TFEB/TFE3 activity." (PMID 33981707, 2021). "We successfully detected SDHB and TFE3 mutations in tissues specimens from SDHD RCC and tRCC patients using the pan-cancer panel analysis." (PMID 32811483, 2020). "ASPSCR1 (↑2.6X twins), is a UBX domain containing tether for SLC2A4, which has a known fusion protein to TFE3 that is involved in certain cancers." (PMID 33115496, 2020). "Wnt signaling plays pivotal roles in regulating tissue regeneration and cancer development, which can be activated by TFE3 expression." (PMID 31043173, 2019). "The nuclear retention of TFE3 fusions promoted the expression of lysosomal genes and other target genes, facilitating cancer cell resistance against an extreme environment." (PMID 30849994, 2019). "Finally, we investigated how the TFE3-mediated modulation of metabolic pathways affects the cancer phenotype." (PMID 39085357, 2024). "We therefore sought to determine whether tRCC cells – which we have shown to have enhanced OXPHOS and a highly reducing environment directly driven by the TFE3 fusion – represent a cancer type vulnerable to reductive stress." (PMID 39149323, 2024). "TFE3‐rearranged RCC is a clinically aggressive malignant tumor." (PMID 38477529, 2024). "Our findings indicated that 42% of patients with RCC with positive TFE3 IHC died from cancer." (PMID 39470841, 2024). "In cancer tissues, loss of FLCN leads to greater TFE3 activation and induction of related pathways." (PMID 38166559, 2024). "We previously focused on the role of TFE3 in autophagy and cancer." (PMID 36906611, 2023). "Thus, TFE3 fusion proteins regulate the metabolism of cancer cells through autophagy differently from TFE3 in normal cells." (PMID 36906611, 2023). "Therefore, an increasing number of researches suggest that these high-expressed TFE3-fusion proteins can function as a major driver of cancer by regulating directly or indirectly downstream target genes." (PMID 35042525, 2022). "In relation to cancer, slow growth induced by FLCN loss and STAT2 upregulation may form a barrier to TFE3-driven renal tumorigenesis in BHD patients." (PMID 33459596, 2021).
cancer (continued). "The contribution of TFEB and TFE3 to cancer is probably complex and context dependent." (PMID 30520728, 2018). "TFE3- and TFEB-associated cancers are generally considered difficult to treat through chemotherapy or irradiation, which may be related to the activation of survival factors, similar to MiTF." (PMID 26872381, 2016). "Furthermore, the nuclear retention of TFE3 fusions could regulate the expression of lysosomal biogenesis genes, thus promoting cancer cells resistance against an extreme environment." (PMID 30849994, 2019). "In addition, the ChIP-seq also revealed that TFE3 fusions could regulate cellular responses to hypoxia stress, which could improve cancer cell resistance to hypoxia and thus promote cancer growth." (PMID 30849994, 2019). "This paradox is mirrored in cancers characterized by constitutive TFEB and TFE3 activation, where elevated mTORC1 activity coexists with increased autophagy." (PMID 41477847, 2026). "This study provides new insights into the molecular mechanisms of TFE3-RCC and suggests avenues for precision treatment of this aggressive cancer." (PMID 39727945, 2024). "Mechanistically, we uncovered that DT-061-mediated modulation of PP2A induced the ISR through the dephosphorylation of TFE3, resulting in chronic upregulation of ATF4 and CHOP to inhibit stress recovery and induce cell death in cancer cells." (PMID 39349971, 2024). "Kidney cancer is a metabolic disease, and most genes (e.g., TFE3, TFEB, FLCN, MITF) involved in this cancer can affect the tricarboxylic acid cycle of cells, which primarily occurs within mitochondria." (PMID 36906611, 2023). "On the other hand, AMPK can promote lysosome biogenesis via TFE3 or BRD4 and protect cancer cells under stresses." (PMID 33917483, 2021). "The MiT/TFE family of transcription factors (MITF, TFE3, and TFEB), which control transcriptional programs for autophagy and lysosome biogenesis have emerged as regulators of energy metabolism in cancer." (PMID 32397616, 2020). "The immunohistochemistry (IHC) findings for each of the cancers showed that neoplastic cells were heterogenous in their nuclear and cytoplasmic expression of MYC, HDAC2 and TFE3." (PMID 31399583, 2019). "Other gene fusions involving transcription factors include NUT (or NUTM1), POU5F1, MAML2, NFIB, PLAG1, TFE3, NOTCH, and PAX8 fusions, imparting spatially and/or stochastically dysregulated expression in multiple different cancer types." (PMID 26684754, 2015). "Translocation-induced overexpression of TFE3 or TFEB fusion proteins is important in proliferation, anchorage independent growth, migration and long term survival of cancer cells." (PMID 21209915, 2010). "Given the critical role of HIF1α in TFE3‐RCC development, inhibiting HIF1α may be an effective therapeutic strategy for treating this cancer subtype." (PMID 39807625, 2025). "Finally, ASPSCR1::TFE3 and VCP demonstrate co-dependence for cancer cell proliferation and tumorigenesis in vitro and in ASPS and RCC mouse models, underscoring VCP’s potential as a novel therapeutic target." (PMID 38326311, 2024). "In summary, these findings indicate that DT-061 mediates TFE3 dephosphorylation via PP2A, subsequentially promoting the transcriptional activation of ATF4 and CHOP that drives irreversible ISR phenotypes and triggers pro-death signals in cancer cells." (PMID 39349971, 2024). "All carcinomas with ASPL/ASPSCR1::TFE3 fusion were classified into the high angiogenesis/stroma/proliferation cluster, whereas half of the MED15::TFE3 and SFPQ/PSF::TFE3 tumors were included in the cluster enriched for EMT, apical junction, TGF-β, WNT catenin, and hypoxia signaling." (PMID 39410016, 2024). "Activation of TFE3, a member of the MiTF/TFE family of transcription factors that regulate energy metabolism and cancer survival may also induce protective autophagy." (PMID 37180606, 2023).